TLR4 (toll like receptor 4)
Diseases named in the same sentence as TLR4 in open-access papers (continued):
Sharing a sentence is not in itself a finding about the gene and the disease.
Cognitive impairment (continued). "Free heme induces cognitive impairment, and the underlying mechanism may involve neuronal apoptosis and microglial inflammation via the TLR4/MyD88/NF-κB signaling pathway." (PMID 38183122, 2024). "The upregulation of AT1R in M1 microglia is associated with inflammation and cognitive impairment through a Toll-like receptor 4 (TLR4)-dependent mechanism; thus, the AT1R-mediated activation of proinflammatory M1 microglia exacerbates inflammation, eventually causing AD." (PMID 36835994, 2023). "We determined whether TLR4 deficiency affects cognitive impairment after LPS-induced neuroinflammation by injecting TLR4 knockout mice (TLR4−/−) with LPS and evaluating memory and motor function." (PMID 38001534, 2023). "In the present study, we demonstrated that quercetin could change inflammatory response via TLR4/NF-κB signaling, thereby attenuating later-life seizure susceptibility, anxiety-related behavior, and cognitive impairment after HINS in rats." (PMID 35223693, 2022). "TLR-4 is known to specifically react with LPS and is implicated in cognitive deficits." (PMID 36670940, 2022). "The TLR4/NF-κB signaling pathway may be implicated in neuroinflammation after SAH and blockage of TLR4 can alleviate cognitive impairment and secondary brain damage after SAH." (PMID 32754015, 2020). "GA at two different doses further regulated the over-expression of pro-inflammatory cytokines via toll-like receptor 4 signaling pathway related to neuro-inflammation, resulting in the inflammatory response alleviation and memory loss and cognitive defects risk reduction." (PMID 31073286, 2019). "Thus, mice with the TLR4 mutation appeared more vulnerable to cognitive deficits associated with the APPswe/PS1dE9 transgenes." (PMID 21827663, 2011). "Following this promising finding, further studies would be needed to determine whether the effect of SSRI antidepressants on microglial morphology linked to TLR4/inflammatory signaling in the dorsal hippocampus may contribute to modulate cognitive impairment induced by long-term alcohol consumption." (PMID 34236532, 2021). "This study reveals that hippocampal neuron necroptosis activates microglia through the TLR4/MyD88 signaling pathway in PTX-induced cognitive impairment, promoting M1 polarization and neuroinflammation." (PMID 40322465, 2025). "In conclusion, activation of the TLR4/NF-κB pathway attenuated the effects of Mor treatment, suggesting that Mor improves cognitive deficits by hindering the TLR4/NF-κB pathway." (PMID 39670511, 2025). "TLR4 inhibition has demonstrated neuroprotective effects in models of doxorubicin-induced cognitive impairment and cerebral ischemia." (PMID 40322465, 2025). "Future studies should focus on in vivo models to confirm the role of TLR4/MyD88 in neuroinflammation and cognitive impairment and further explore its therapeutic potential." (PMID 40322465, 2025). "To further explore the molecular mechanisms by which Mor ameliorates cognitive impairment, we assessed the effect of Mor on TLR4." (PMID 39670511, 2025). "Based on these findings, this study investigated the role of TLR4 in PTX-induced cognitive impairment and the effect of inhibiting hippocampal neuron necroptosis on TLR4 expression." (PMID 40322465, 2025). "Here, it is demonstrated that Listerin suppresses neuroinflammatory signaling and cognitive impairment in AD models by triggering IRE1α‐mediated TLR4 mRNA decay." (PMID 40448625, 2025). "Some studies suggested that high uric acid levels mediated the development of cognitive impairment by activating the Toll-like receptor 4 (TLR4)/NF-ΚB signaling pathway, inflammation, oxidative stress, and endothelial dysfunction." (PMID 40671786, 2025). "This is particularly relevant considering the potential link between TLR4 signaling and cognitive deficits, a critical and often challenging aspect of schizophrenia treatment." (PMID 40153412, 2025).
Cognitive impairment (continued). "Compounds designed to target TLR4 have demonstrated an ability to reduce cognitive impairments and enhance AD-like symptoms in animal models." (PMID 39936960, 2025). "This is distinct from previous studies which did not explore the connection between neuron necroptosis and microglial activation via TLR4/MyD88 in the context of PTX-induced cognitive impairment." (PMID 40322465, 2025). "Downregulation of TREM2 leads to cognitive impairment, Aβ accumulation, and neuroinflammation, increasing the release of inflammatory factors through the Toll-like receptor 4 (TLR4)-mediated MAPK signaling pathway, thereby increasing inflammation." (PMID 41256774, 2025). "It helps to reduce cognitive impairment, neuroinflammation, and oxidative stress by activating TLR4/NFκB, Nrf2/HO-1, and BDNF/VEGF signaling pathways." (PMID 39650161, 2024). "It has been shown in a rat model of subarachnoid hemorrhage that H2S can reduce cognitive deficits by inhibiting the neuroinflammation induced by the TLR4/NF-κB signaling pathway that activates microglial cells." (PMID 37445920, 2023). "They discovered that rats administered nobiletin exhibited less cognitive impairment and lower levels of Toll-like receptor 4 (TLR4), NF-κB, and TNF-α but higher expression of Nrf2 in the hippocampus." (PMID 37767395, 2023). "By establishing an animal model of IL-17A overexpression, we discovered that IL-17A increases the level of TNF-α in the brain through the TLR4/NF-κB signalling pathway, aggravates neuroinflammation, and thus exacerbates cognitive impairment." (PMID 38098004, 2023). "Excessive activation of inflammatory pathways such as TLR4/NF-κB/NLRP3 and TLR4/Akt/mTOR promotes an increase in the central nervous system inflammatory response and participates in the occurrence and development of cognitive impairment." (PMID 37576498, 2023). "Inhibition of the TLR4 signaling pathway can alleviate neuronal pyroptosis and cognitive impairment in AD models." (PMID 38020781, 2023). "Recent clinical studies have observed significantly increased levels of Enterobacteriaceae, TLR4, LPS, and peripheral inflammatory markers in the gut of patients with post-stroke cognitive impairment." (PMID 37249983, 2023). "It is indicated that GAS ameliorated REM sleep-deprivation-induced cognitive impairment and neuronal injury by inhibiting the TLR4/NF-κB signaling pathway." (PMID 36831722, 2023). "Cognitive impairment is caused by HMGB1 (High-mobility group box protein 1), RAGE (Receptor for Advanced Glycation End Products), and TLR4 (Toll-like receptor 4) in hyperglycemic conditions." (PMID 36497027, 2022). "The researchers proposed acupuncture attenuates cognitive impairment associated with inflammation through inhibition of the miR-93-mediated TLR4/MyD88/NF-κB signaling pathway in experimental VD, and acupuncture may be an underlying TLR4 inhibitor for the treatment of VD." (PMID 36204718, 2022). "HMGB1 causes neuroinflammation and cognitive impairment through direct binding to advanced glycation end products (RAGE) and Toll-like receptor 4 (TLR4)." (PMID 36552192, 2022). "ProBiotic-4, a probiotics mix, alleviated cognitive deficits in aged SAMP8 mice by suppressing TLR4-mediated NF-κB activation." (PMID 35889931, 2022). "Taken together, these findings suggest that quercetin inhibit proinflammatory response via TLR4/NF-κB signaling pathway, thereby attenuating cognitive impairment and hippocampal dysfunction in later-life of rats following HINS." (PMID 35223693, 2022). "Dex partly through inhibiting microglia transformation to the M1 polarization state and inactivating the TLR4/NF-kB pathway attenuates the cognitive disorders in mice." (PMID 35815058, 2022). "It has been reported that AS-IV attenuates cognitive impairments partly through its anti-inflammatory activities via the suppression of inflammasome overactivation and the Toll-Like Receptor 4 (TLR4) signaling pathway." (PMID 34482800, 2021).
Cognitive impairment (continued). "Inside the brain, endotoxin binds to microglial TLR4, activating these cells, probably contributing to cognitive impairment, or “brain fog” experienced by many ME/CFS patients." (PMID 34248502, 2021). "β-glucan inhibits TLR4 endocytosis, preventing LPS activation of microglia and the subsequent cognitive impairment." (PMID 34248502, 2021). "In this study, we found a pronounced increase of TLR4 expression in B2M-treated mice, which confirming a possible correlation with B2M-induced cognitive impairment." (PMID 32059688, 2020). "We have previously reported that PMFE improves cognitive impairment induced by decreased blood flow through an inhibitory effect on the toll-like receptor 4(TLR4)/myeloid differentiation primary response 88/ nuclear factor (NF)-κB signaling pathways." (PMID 33322041, 2020). "The evidence demonstrated the role of TLR4 in learning and memory function of Alzheimer’s disease (AD), we wondered if TLR4 affected B2M-induced cognition impairment." (PMID 32059688, 2020). "Several reports suggest that SFAs activate TLR4‐dependent signaling pathways that increase inflammatory responses in microglia and induce brain inflammation, thus modulate cognitive impairments." (PMID 32994939, 2020). "In conclusion, the present research indicated that EA protects mice against SD-induced cognitive impairment and anxiety by inhibiting TLR4 and activating Nrf2." (PMID 32433038, 2020). "Lipopolysaccharide (LPS), a major bacterial Toll-like receptor 4 (TLR4) ligand, can trigger an innate immune response, induce neuroinflammation, and influence the function of neuronal cells, thus leading to cognitive impairment." (PMID 31883536, 2019). "Based on the results of our study, LPS induces neuroinflammation via the TLR-4 signaling pathway, leading to cognitive impairment." (PMID 30962497, 2019). "FN has also suppressed cognitive impairment in diabetic mice, possibly through the downregulation of TLR4/NF-κB signaling and NLRP3 inflammasome." (PMID 31561418, 2019). "In rats, alcohol exposure during adolescence activates HMGB1/TLR4 danger signaling in the brain, and this activation persists into adulthood correlating with the presence of cognitive deficits." (PMID 30687006, 2018). "Inflammation plays an important role in cognitive impairment, which is mediated by activation of the TLR4 signaling pathway." (PMID 29426327, 2018). "Besides TLR4 signaling, early life stress can alter oxidative stress and kynurenine metabolism with a decrease in neuroprotective ratio which may underlie the subsequent behavioral and cognitive deficits." (PMID 28611665, 2017). "Therefore, this study aimed to explore the therapeutic potential of C. longa-derived CL-80 and arturmerone against Aβ-induced neuroinflammation and cognitive deficits by targeting the TLR4/NF-κB signaling pathway." (PMID 40967916, 2025). "In summary, this study demonstrated that hippocampal neuron necroptosis activates microglia through the TLR4/MyD88 signaling pathway in PTX-induced cognitive impairment, promoting M1 polarization and neuroinflammation, while inhibiting necroptosis promotes M2 polarization and neuroprotection." (PMID 40322465, 2025). "Whether baicalein can prevent long-term cognitive impairments induced by repeated neonatal sevoflurane exposure, and whether this effect involves TLR4/NF-κB modulation, remains unknown." (PMID 41281895, 2025). "Consistently, studies have proven that regulating the TLR4/MyD88/NF-κB pathway in microglia might take part in neuroinflammation and cognitive impairment." (PMID 38183122, 2024). "We provided several lines of evidence supporting the hypothesis that free heme could induce neuroinflammation and cognitive deficits by microglial activation via the TLR4/MyD88/NF-κB signaling pathway." (PMID 38183122, 2024).
Cognitive impairment (continued). "Interestingly, a previous study of our group showed that Spike-induced cognitive impairment in mice triggers innate immunity activation through TLR4, culminating in microgliosis, neuroinflammation, and synaptic pruning." (PMID 38678084, 2024). "TLR4 hyperactivity was related to cognitive impairment and reduced white matter integrity." (PMID 38891900, 2024). "Supplementation with LP EMCC-1039 may improve NAFLD and cognitive impairment by affecting the intestine–liver–brain axis and hippocampal TLR4/BDNF signaling pathway." (PMID 37249983, 2023). "Furthermore, abnormal BDNF permeability and cognitive impairment were observed in older mice, correlated with increased TLR4 expression and decreased phosphorylation of serine 9, an inhibitory residue in GSK-3β protein." (PMID 38001481, 2023). "TLR4 activation can reduce hippocampal pyramidal neuron dendrite length and impair hippocampal-dependent spatial reference memory in an inflammation-dependent manner, thus suggesting the potential for TLR4 activation by UA which lead to cognitive impairment." (PMID 35530021, 2022). "Trigonelline is also a plant alkaloid with antioxidant, anti-inflammatory, and neuroprotective effects, which could reduce LPS-induced cognitive impairment and inflammatory response by regulating NF-κB/Toll like receptor 4 and acetylcholinesterase activity." (PMID 35770099, 2022). "We observed that KXS upregulated AKT phosphorylation, suppressed GSK3β and CDK5 activation, and inhibited the TLR4/MyD88/NF-κB signaling pathway to attenuate Tau hyperphosphorylation and neuroinflammation, thus suppressing neuronal apoptosis and improving the cognitive impairment of aged SAMP8 mice." (PMID 35303280, 2022). "Pretreatment with Dex, partly through inhibiting microglia transformation to the proinflammatory M1 polarization state and inactivating of the TLR4/NF-kB pathway decreases inflammatory response, attenuates the cognitive disorders in mice following tourniquet used." (PMID 35815058, 2022). "Combined protein detection of CRP, homocistein (Hcy) and Toll-like receptor 4 (TLR4) in serum have shown biomarker value for cognitive abnormalities related with Cerebral Small Vessel Disease (SVD) which is the most common vascular abnormality associated with VD." (PMID 36362875, 2022). "Treatment with EA may reduce the blood ammonia level, modulate inflammatory factors, ameliorate brain necrosis and apoptosis, and improve cognitive impairment through regulation of TLR4/MyD88/NF-κB and p38MAPK/STAT3 signaling pathways." (PMID 34630618, 2021). "The secreted glycoprotein myeloid differentiation factor 2 (MD2) functions as an activator of the Toll-like receptor 4 (TLR4) inflammatory pathway, and α5GABAA receptors (α5GABAARs) are known to play a key role in regulating inflammation-induced cognitive deficits." (PMID 34530841, 2021). "This study was designed to verify the hypothesis that acupuncture improves cognitive impairment via modulating the miR-93-mediated TLR2/TLR4 signaling pathway to suppress the inflammatory responses." (PMID 32850002, 2020). "Moreover, the improvement of cognitive deficits was accompanied by the attenuation of inflammatory injury and apoptosis via TLR4 activation and its downstream signaling pathways." (PMID 32059688, 2020). "Furthermore, VIPER, which is a TLR-4-specific inhibitory peptide, prevented the LPS-induced neuroinflammation and cognitive impairment." (PMID 30962497, 2019). "However, the suppressive effects of GA against LPS-induced neuroinflammation and cognitive impairment via TLR4 signaling pathway are not yet well understood." (PMID 31073286, 2019). "Several evidence indicates that alcohol induces the TLR4 signaling in the PFC, triggering the induction of a cascade of pro-inflammatory mediators that affect, among others, cognitive impairments and anxiety-like behaviors associated with the alcohol abuse." (PMID 28223925, 2017).
Cognitive impairment (continued). "Importantly, Mor blocked the TLR4/NF-κB pathway, suggesting that it may alleviate cognitive deficits in aged mice by modulating the TLR4/NF-κB pathway." (PMID 39670511, 2025). "Additionally, in lipopolysaccharide (LPS)-induced cognitive impairment models, trigonelline alleviated hippocampal oxidative stress and inflammation by suppressing the NF-κB/ Toll-like receptor 4 (TLR4) signaling pathway and modulating AChE activity, ultimately improving cognitive performance." (PMID 41334328, 2025). "Finally, we show that the TLR4/MyD88/NF-κB signaling pathway may be involved in free heme-induced neuroinflammation and cognitive deficits." (PMID 38183122, 2024). "Herein, by using Western blot, immunofluorescence studies, and some biochemical assays, we investigated whether the oral administration of kojic acid might alleviate LPS-induced TLR4-mediated neuroinflammation, oxidative stress, and memory and cognitive impairment in vivo." (PMID 39185307, 2024). "However, whether GAS can ameliorate REM sleep-deprivation-induced cognitive impairment through the TLR4/NF-κB pathway remains unknown." (PMID 36831722, 2023). "TLR4-mediated neuroinflammation preferentially affects glial cells such as microglia oligodendrocytes, which mainly constitute white matter microstructure and white matter microstructural dysconnectivity has been related to cognitive impairment in schizophrenia." (PMID 36051545, 2022). "Additionally, TLR4 signaling reduces neurogenesis and results in cognitive impairment." (PMID 31231221, 2019). "Supporting this concept, studies have demonstrated that promoting M2 polarization-for instance, through TLR4 inhibition in APP/PS1 mice-exerts neuroprotective effects and ameliorates cognitive deficits." (PMID 41378217, 2025). "In this exploratory study, we found that NBP effectively ameliorates cognitive impairment and attenuates neuroinflammation in chronic hypertension-induced CSVD, primarily through modulation of the TLR4/NF-κB signaling pathway." (PMID 40919222, 2025). "Targeting neuroinflammation with alogliptin, a dipeptidyl peptidase-4 inhibitor, has shown neuroprotective effects by targeting the TLR4/MYD88/NF-κB signaling cascade against lipopolysaccharide (LPS)-induced neuroinflammation and cognitive impairment in mice." (PMID 40801649, 2025). "Elevated TLR signaling through TLR2, TLR4, and TLR9 correlates with frailty, cognitive impairment, and functional decline." (PMID 41373468, 2025). "Intraperitoneal injection of hemin induced cognitive impairment, increase of CD91 + cells, up-regulation of TNF-α and IL-1β, down-regulation of IL-6, activation of microglia, and activation of the TLR4/MyD88/NF-κB signaling pathway in rat brain." (PMID 38183122, 2024). "Curcumin improves cognitive impairment by inhibiting neuroinflammation-induced activation of microglia, modulating the TREM2/TLR4/NF-κB pathway, and reducing NLRP3-dependent pyroptosis." (PMID 38020781, 2023). "Baicalin alleviates cognitive impairment and protects neurons from microglia-mediated neuroinflammation via inhibiting NLRP3 inflammasomes and the TLR4/NF-κB signaling pathway." (PMID 36838564, 2023). "HMGB1/TLR4/IL-1β/IL-1R pathway, HMGB1/TNF-α/TRADD pathway, and TRAF-2 are the key initiators of neuroinflammation for epilepsy and cognitive impairments." (PMID 35656438, 2022). "In doxorubicin (DOX)-impaired rats, galangin significantly mitigates cognitive impairment and neurotoxicity via the NOX-1/Nrf-2/HMGB1/TLR4 and TNF-α/MAPKs/RIPK/MLKL/BDNF pathways." (PMID 36015161, 2022). "For example, TLR4/MyD88 signaling activation by S100A8 promotes neuroinflammation and contributes to tibial fracture surgery-induced cognitive disorders." (PMID 34530841, 2021). "Treatment with NaHS significantly decreased the cognitive impairment of rats after SAH and simultaneously reduced the expression of TNF-α, TLR4, and NF-κB p65 and alleviated the nuclear translocation of NF-κB p65 (p < 0.05)." (PMID 32754015, 2020).